NRAS (NRAS proto-oncogene, GTPase)
Diseases named in the same sentence as NRAS in open-access papers (continued):
Sharing a sentence is not in itself a finding about the gene and the disease.
melanoma (continued). "However, NRAS-mutant melanoma, a subtype comprising 15–25% of melanomas, remains refractory to most current treatments and is associated with a poorer prognosis compared to BRAF-mutant or wild-type variants." (PMID 40563669, 2025). "Class I mutations were almost exclusively found in melanomas and were always accompanied by co-driver MAPK mutations, predominantly in BRAF or NRAS, and may contribute to aggressive melanoma behaviour." (PMID 40107205, 2025). "Specifically, melanoma cells have relatively high FNTB levels and are commonly mutated for NRAS." (PMID 39995872, 2025). "For example, BRAF and NRAS mutations are prevalent in superficial spreading and nodular melanomas, NF1 loss is associated with chronic sun-damaged melanomas, KIT mutations are more common in acral and mucosal disease, and GNAQ/GNA11 mutations characterize uveal melanoma." (PMID 41283484, 2025). "Similarly, combination therapy combining trametinib with palbociclib resulted in NRAS-mutant melanoma models." (PMID 41516092, 2025). "Early-onset melanomas, which typically occur in middle-aged adults at sites with low cumulative sun damage (CSD), often harbor somatic BRAF or NRAS mutations, are associated with a higher number of nevi, and are primarily linked to intermittent UV exposure during childhood." (PMID 39941357, 2025). "The simultaneous inhibition of MAPK, AKT, and/or CD133 and focusing on specific AKT paralogues may be viable strategies for the treatment of recalcitrant NRAS-mutant melanoma." (PMID 39996721, 2025). "In particular, melanoma patients harboring BRAF and NRAS mutations may benefit from therapies targeting ACKR2." (PMID 40248897, 2025). "Mutations in BRAF (rapidly accelerated fibrosarcoma B-type) and NRAS (neuroblastoma RAS viral oncogene homolog) are the most common genetic drivers of melanoma, with BRAFV600E occurring in over 50% of cases and NRAS mutations, such as Q61R, observed in 15−20% of cases." (PMID 40141318, 2025). "Importantly, targeting S-nitrosylation in NRAS-mutant melanoma holds therapeutic promise by reversing drug resistance and stimulating anti-tumor immune responses." (PMID 40563669, 2025). "When brimarafenib was combined with mirdametinib, accumulating effect was observed across all patient‐derived melanoma cell lines, irrespective of NRAS mutational status and known resistance to MEKi." (PMID 41199020, 2025). "BRAF-mutant melanomas have a significantly higher activation of AKT than NRAS-mutant melanomas." (PMID 40076927, 2025). "This advantage may address the challenge of targeting NRAS-mRNA, which we found to be present in both nuclear and cytoplasmic compartments of NRAS-mutant melanoma cells." (PMID 40473796, 2025). "Given the unsatisfactory results of small molecule inhibitor treatment in the specific focus of NRAS-mutant melanoma, our findings suggest that improvement may involve combinatorial approaches that include the inhibition of NRAS." (PMID 40473796, 2025). "In particularly difficult cases, molecular analysis may be helpful; TMMs are known to exhibit highly similar mutational landscapes to conventional melanomas (e.g., mutations in NF1, NRAS; variable BRAF V600E)." (PMID 40090763, 2025). "Mutations in the RAS/BRAF axis system, especially NRAS, are common in sinonasal melanomas, often even more common than other common melanoma mutations such as BRAF." (PMID 41369373, 2025). "Regarding NRAS mutation, their frequency did not vary significantly across melanoma subtypes, though mutation sites differed, with Q61 predominant in cutaneous and G12 in mucosal melanomas." (PMID 39757723, 2025).
melanoma (continued). "Nelfinavir, an HIV-1 protease inhibitor, is an essential salvage therapy for treating non-mutational drug tolerance developed in BRAF- and NRAS-mutant melanomas during the therapy phase due to a PAX-3-mediated increased expression of the MITF gene." (PMID 41516092, 2025). "Considering that NRAS mutations are frequently reported as resistance mechanisms in BRAF-mutated melanomas treated with BRAF inhibitors, we investigated the effects of vemurafenib on melanoma cells harboring the NRASQ61R mutation." (PMID 40141318, 2025). "ASOs designed for the non-mutated NRAS sequence eliminate NRAS-dependent melanoma cells while sparing NRAS wild-type cells." (PMID 40473796, 2025). "Also, NRAS-specific S-nitrosylation appears critical for MEKi resistance and immune evasion in melanoma, making it a promising therapeutic target." (PMID 40563669, 2025). "The second most frequently mutated oncogene in melanoma is NRAS, but unlike mutant KRAS, the gene defect affects the Q61 codon of exon 3 and selective inhibitors have not yet been developed." (PMID 40361349, 2025). "We chose NRAS over BRAF because there is more frequent CDH1 downregulation in NRAS-mutant melanomas and a lack of targeted therapies for NRAS-mutated cases." (PMID 40500450, 2025). "In co-culture with two melanoma cell lines, ME4405 and SK-MEL-28 (which harbor BRAF and NRAS mutations, respectively), we observed that knockdown of CCNB1 in melanoma cells increased the proportion of NK-92MI expressing CD69 and CD107a, which are key markers of NK cell activation." (PMID 40430484, 2025). "BRAF, NRAS, or NF1 mutations can co-occur with C/T mutations in the promoter region of the telomerase reverse transcriptase (TERT) gene, which are frequently observed in melanoma, occurring in 30–85% of cases depending on disease stage." (PMID 39859576, 2025). "Immunotherapies, especially immune checkpoint inhibitors, may be particularly effective in NRAS-mutant melanoma." (PMID 40508177, 2025). "Importantly, the Mitogen Activated Protein Kinase (MAPK) pathway has been identified as a major culprit, with BRAF V600, NRAS Q61 and NF1 mutations driving 60%, 20% and 4% of melanomas, respectively." (PMID 41168392, 2025). "Also, Spitz melanomas are thought to generally have a more favourable prognosis than melanomas with BRAF, NRAS, or NF1 mutations." (PMID 40107205, 2025). "Furthermore, advancements in molecular oncology have facilitated the detection of mutations in genes like BRAF, NRAS, and c-KIT in canine melanomas." (PMID 41394861, 2025). "Additionally, we found that atezolizumab and bevacizumab extended the PFS and OS of NRAS mutant patients to levels similar to those of wild‐type patients, and NRAS mutant mucosal melanoma exhibiting enhanced angiogenesis feature with elevated VEGFA expression." (PMID 39757723, 2025). "One study identified acquired oncogenic mutations in NRAS and the loss of CDKN2A in BRAF-V600E-mutant melanoma tumors from two patients who progressed on BRAF/MEK inhibitors, suggesting that the reactivation of MAPK and the activation of cell cycle pathways contribute to resistance." (PMID 40282469, 2025). "When MEKi was previously compared to the long-standing but limitedly proven cytostatic dacarbazine, only modest responses were observed in the treatment of NRAS-mutant melanoma, and a clinical trial indicated that NRAS-mutant melanoma patients only show limited benefit to MEKi54." (PMID 40473796, 2025).
melanoma (continued). "Translationally, the panRAF inhibitor naporafenib combined with trametinib produced preliminary antitumor activity in a phase Ib expansion cohort of previously treated NRAS‐mutant melanoma, catalyzing the ongoing SEACRAFT‐2 pivotal phase III trial (NCT06346067)." (PMID 41199020, 2025). "Most notably, the ASOs inhibited NRAS-mutant melanoma growth in vitro and in vivo." (PMID 40473796, 2025). "To test, whether the specific vulnerability of NRAS-mutant cancer cells to NRAS inhibition expands beyond melanoma, we tested if the treatment may impact cell-growth in NRAS-mutant multiple myeloma (MM, H929) and small cell lung cancer (SCLC, SW1271) cells." (PMID 40473796, 2025). "Our findings underscore that the maintenance of unaltered NRAS-mRNA expression may be a specific vulnerability of NRAS-mutant melanoma cells, eliminating the need to solely focus on the inhibition of mutant NRAS." (PMID 40473796, 2025). "Next, we investigated NRAS-dependency in the subgroup of all melanoma cell lines." (PMID 40473796, 2025). "Additional mutated driver genes in melanoma other than BRAF, such as NF1 and NRAS, might also impact the treatment choice." (PMID 40004220, 2025). "Finally, early-phase clinical trials evaluating the sequential or combinatorial use of NOS and MEK inhibitors in NRAS-mutant melanoma are warranted." (PMID 40563669, 2025). "Inhibitors of STK19 have shown efficacy in a mouse model of NRAS-induced melanoma." (PMID 39858030, 2025). "In NRAS-mutant melanoma, S-nitrosylation emerges as a critical regulator of this process." (PMID 40563669, 2025). "Furthermore, the mutation rate of melanoma is one of the highest among different cancers, with mutations seen primarily in the BRAF, NRAS, and MEK genes, increasing the immunogenicity of tumor cells." (PMID 39941844, 2025). "Instead, a comparative analysis of melanoma cell lines derived from primary tumors or the metastasis of human, canine, and equine species showed comparable mutations in proto-oncogenes BRAF, NRAS, and KIT, which are well-known factors regulating proliferation and apoptosis in human melanoma." (PMID 40563676, 2025). "BRAF and NRAS mutations were found in 20% of spitzoid melanomas in one study, which was lower than the 61% in nonspitzoid melanoma." (PMID 39415471, 2025). "We have previously demonstrated that the treatment of mice bearing genetically derived inducible melanoma tumors (BRAF/PTEN or NRAS/INK4a) with the CXCR1/2 antagonist (SX-682) inhibited tumor growth and increased activated CD8+ T cells, partly by reducing the intratumoral MDSCs." (PMID 40904502, 2025). "Additionally, MC1R variants heighten susceptibility to UV-induced melanoma through oxidative stress and mutations in genes like BRAF and NRAS." (PMID 39859464, 2025). "However, NRAS-mutant melanomas exhibit normal PTEN levels, suggesting BRAF-mutant and NRAS-mutant tumors differ in their mechanisms of progression towards BMs." (PMID 40076927, 2025). "First, our experimental models primarily reflect features of acral melanoma and the identified high-risk TEAD3 + subgroup; thus, the generalizability to other melanoma subtypes (e.g., BRAF or NRAS mutant, or triple wild-type tumors) requires further validation." (PMID 41034991, 2025). "This is in agreement with the literature, as vemurafenib does not exert cytotoxicity in melanoma cells presenting the NRAS mutation." (PMID 40141318, 2025). "For example, none of the five melanomas with a RASGRF fusion identified in this study had co-occurring activating BRAF or NRAS mutations." (PMID 40615519, 2025).
melanoma (continued). "The activation of P2RX7 was associated with improved therapeutic responses, and when combined with targeted therapies, it could help delay the onset of acquired resistance in NRAS-mutant melanoma." (PMID 40872623, 2025). "MEK inhibitors, particularly binimetinib, have demonstrated activity in NRAS-mutant melanoma." (PMID 40508177, 2025). "The discrepancy in tumor location between BRAF- and NRAS-mutated melanomas can be attributed to the differing sensitivity of BRAF- and NRAS-mutant melanocytes to ultraviolet (UV) light-induced carcinogenesis, with BRAF-mutated melanocytes exhibiting greater sensitivity to UV-mediated damage." (PMID 39857682, 2025). "Among the melanoma cell lines analyzed, three, Mel Il, Mel Ibr, and Mel Z, harbored hyperactivating mutations in the BRAF gene, while one, Mel Mtp, carried a mutation in the NRAS gene." (PMID 39772250, 2024). "A study using IMS detected greater proteomic changes in BRAF- and NRAS-mutated melanomas compared with melanomas without the mutations." (PMID 38247727, 2024). "Naporafenib, a RAF dimer selective inhibitor, in combination with the MEK inhibitor trametinib or in combination with the ERK inhibitor LTT462, is being explored in a clinical trial for its efficacy in advanced metastatic KRAS- or BRAF-mutant NSCLC or in NRAS-mutant melanoma (NCT02974725)." (PMID 38731852, 2024). "Throughout this review, we have explored the genetic landscape of melanoma, highlighting the importance of mutations in key genes such as BRAF, NRAS, and KIT, as well as the relevance of epigenetic modifications and interactions with the tumor microenvironment." (PMID 39200315, 2024). "NRAS and KIT gene mutations are associated with the melanoma subtype in the Australian group." (PMID 39195270, 2024). "Additionally, it is well known that primary melanomas can arise from different driving mutations, such as those in BRAF or NRAS." (PMID 39062529, 2024). "The TCGA network, employing whole exome sequence examination in patients diagnosed with local and/or advanced melanoma, recognized four unique genomic subtypes: those with mutations in NF1, mutations in BRAF, mutations in NRAS, and those categorized as triple wild type." (PMID 38539531, 2024). "Additionally, miR-146a, which targets genes like NRAS, and miR-155, known to modulate immune responses, are also noted for their roles in melanoma development and progression." (PMID 38785501, 2024). "The primary mutations discussed in melanoma research include BRAF, PTEN, and NRAS mutations." (PMID 38835341, 2024). "Treatment of NRAS-mutant melanoma cells with MEK and CDK4/6 inhibitors induced two divergent drug responses: fast-adapting cells characterised by increased ion transmembrane transport and an immune-like state, and slow-adapting cells with features of senescence." (PMID 38241976, 2024). "In addition, p38 MAPK activity was shown to be inhibited in all NRAS-mutant melanoma cell lines following corin treatment, with associated increases in DUSP1 and DUSP5 expression." (PMID 38300709, 2024). "Melanomas on skin intermittently exposed to sun frequently carry somatic BRAF mutations and have a higher nevus count, while melanomas chronically exposed to solar UVR have a low nevus count and NRAS and KIT mutations." (PMID 38927967, 2024). "However, the ways in which these drugs inhibit activity under the two major activating mutations in melanoma, BRAF V600E and NRAS Q61 hotspot mutations, and the corresponding drug dose landscape are still being explored." (PMID 39199684, 2024). "While Bliss excess showed drug additivity across the entire dose–response landscape in BRAF V600E/K lines, NRAS mutant melanoma lines presented a narrow concentration range in which the combination of panRAF and MEK inhibitors was highly synergized in inhibiting cancer growth." (PMID 39199684, 2024).
melanoma (continued). "In this single-center retrospective cohort study, we further analyzed the antitumor activity and safety of triple-targeted therapy (TTT): REGO + BRAF/MEKi, specifically in the AJCC stage IV-M1dBRAF- and NRAS-mutant melanoma patients, refractory to standard-of-care." (PMID 39682270, 2024). "Overall, our findings contribute to a better understanding of the molecular mechanisms underlying melanoma resistance to targeted therapies and provide insights into potential strategies to improve treatment outcomes for patients with BRAF- or NRAS-mutant melanomas." (PMID 39436655, 2024). "In some patients, we could also exclusively detect mutations in melanoma driver genes (BRAF, NRAS, MAP2K1, KIT) suggesting that CTC analysis could complement ctDNA analysis for relevant clinical implications in personalized medicine in oncology." (PMID 38898234, 2024). "NRAS is the second most frequently mutated oncogene in melanoma; however, no effective treatment for NRAS mutations exists." (PMID 38462618, 2024). "Our results may also provide insight into the mechanisms of ERK pathway activation in NRAS-mutant melanomas." (PMID 39436655, 2024). "Moreover, in melanoma cells with BRAF and NRAS mutations, HSPB8 exerts this role through the induction of autophagy, which counteracts cell growth." (PMID 38775220, 2024). "Typically, NF1 mutations are found in melanomas that lack mutations of BRAF and NRAS." (PMID 38247727, 2024). "Moreover, compared to BRAF-mutant tumors, NRAS-mutant melanomas tend to be thicker, with increased mitotic rates, usually occurring in older patients (>55 years) with a history of chronic UV exposure." (PMID 38396984, 2024). "However, data correlating clinical outcomes and responses to ICI for NRAS mutant melanoma are mixed." (PMID 38611025, 2024). "Furthermore, among advanced melanoma patients treated with first-line ICI, NRAS mutations were commonly observed, primarily Q61R and Q61K (present in 49% of 637 patients)." (PMID 39582535, 2024). "Preclinical models suggest that combining RAF dimers with MEK inhibition may hold promise for NRAS-mutant melanoma." (PMID 39682270, 2024). "Similarly, mutations in NRAS result in aberrant activation of the MAPK pathway, promoting melanoma cell proliferation and survival." (PMID 39200315, 2024). "However, we did not observe any associations between the most frequent somatic mutations (BRAF, CDKN2A, PTEN, NRAS) and Treg infiltration in AYA melanoma." (PMID 38589406, 2024). "Another mutation encountered in melanoma is the NRAS- mutation which is found in 20% nonacral melanomas." (PMID 39741925, 2024). "BVD-523 is a small-molecule inhibitor of ERK kinase that has completed phase I testing and has demonstrated activity in patients with BRAF/MEK-inhibitor refractory, BRAF-mutant melanoma as well as in a patient with NRAS-mutant melanoma with a reasonable safety profile." (PMID 38683104, 2024). "Acral melanoma typically has a lower mutation burden and lower rates of B-RAF proto-oncogene (BRAF) and neuroblastoma RAS viral oncogene homolog (NRAS) mutations as compared to its non-acral melanoma counterparts." (PMID 39001457, 2024). "Most melanomas arise de novo from fields of melanocytic atypia, particularly in sun-damaged skin, and are associated with BRAFnonV600E (such as BRAFV600K, K601E, G469A), NRAS (NRASQ61R, Q61K), and NF1 mutations." (PMID 39201498, 2024). "Furthermore, identifying personalized neoantigens in melanomas with BRAF and NRAS mutations is pivotal in constructing immunogenic mRNA vaccines, paving the way for highly personalized melanoma therapy." (PMID 39582535, 2024).